HSDL2 (hydroxysteroid dehydrogenase like 2)
Description:
Has apparently no steroid dehydrogenase activity. Controls bile acid (BA) and lipid metabolism in response to nutritional cues.
Synonyms: C9orf99; SDR13C1
Tractability: Small molecule: a structure with a bound ligand is known; it has a high-quality binding pocket. PROTAC: ubiquitination databases record sites on it; its protein half-life has been measured.
Target class: Enzyme; Oxidoreductase
Gene: Protein-coding gene on chromosome 9 (112,380,051 to 112,472,408, forward strand). Ensembl gene ENSG00000119471.
Subcellular location: Peroxisome; Mitochondrion
Subcellular location (Human Protein Atlas): Mitochondria
Gene Ontology:
Molecular function: steroid dehydrogenase activity
Biological process: cholesterol homeostasis
Cellular component: membrane; mitochondrion; peroxisome
Genetic constraint (gnomAD): Loss-of-function variants: 12 observed, 16.57 expected, observed/expected ratio (o/e) 0.72, 90% interval 0.46 to 1.17. The upper end of that interval is the gene's LOEUF score, 1.17, which puts it in group 5 of 6, group 1 being the genes least tolerant of losing a copy. Missense variants: 209 observed, 228.48 expected, observed/expected ratio (o/e) 0.91, 90% interval 0.82 to 1.03. Synonymous variants: 69 observed, 74.61 expected, observed/expected ratio (o/e) 0.92, 90% interval 0.76 to 1.13.
Homologues: Orthologues: chimpanzee HSDL2 (100% identical), macaque HSDL2 (96% identical), pig HSDL2 (89% identical), rabbit HSDL2 (88% identical), mouse Hsdl2 (87% identical), guinea pig HSDL2 (85% identical), rat Hsdl2 (85% identical), dog HSDL2 (78% identical), tropical clawed frog hsdl2 (73% identical), zebrafish hsdl2 (68% identical), Drosophila melanogaster Hsdl2 (55% identical), Caenorhabditis elegans dhs-6 (54% identical), and 6 more. Paralogues in human: DHRS1 (17% identical), CBR1 (15% identical), CBR3 (15% identical), DHRS7 (13% identical), DHRS7B (13% identical), HSD11B1 (13% identical), DHRS2 (12% identical), DHRS7C (12% identical), DHRS11 (11% identical), RDH8 (11% identical), DHRS4 (11% identical), HSD11B1L (11% identical), and 1 more.
Diseases named in the same sentence as HSDL2 in open-access papers:
HSDL2 is named in the same sentence as 29 diseases in open-access papers, as found by Europe PMC text mining. Sharing a sentence is not in itself a finding about the gene and the disease. The quoted sentences say what the papers report.
ovarian carcinoma (5 papers, 2018 to 2022). A malignant neoplasm originating from the surface ovarian epithelium. "Knockdown of HSDL2 resulted in decreased growth rates in glioblastoma cell lines, and inhibited cell proliferation, colony formation, motility, and tumorigenesis in ovarian cancer cells underlining an important role for peroxisomes in these tumor types." (PMID 30219925, 2018). "HSDL2 was in highly expressed in human ovarian cancer and was positively correlated with tumor progression and lymphatic metastasis, meanwhile, HSDL2 knockdown inhibited tumorigenesis in vivo or vitro." (PMID 35948893, 2022). "There were only 4 PPAR-TRGs (AP2A2, DOCK4, HSDL2, and PDK4) out of 269 DEGs, which are associated with platinum chemosensitivity in ovarian cancer." (PMID 33613670, 2021). "Normally, HSDL2 is highly expressed in the liver, kidney, prostate, testes and ovaries, but researchers also found the high expression level of the HSDL2 in various cancers such as cholangiocarcinoma, ovarian carcinoma, glioma." (PMID 33738911, 2021). "Another recently identified peroxisomal protein, HSDL2 (hydroxysteroid dehydrogenase-like 2) also appears to be up-regulated in glioblastomas and ovarian cancer." (PMID 30219925, 2018).
glioma (4 papers, 2019 to 2022). A benign or malignant brain and spinal cord tumor that arises from glial cells (astrocytes, oligodendrocytes, ependymal cells). "It was reported that HSDL2 could mediate cell proliferation and tumor growth in glioma via Akt-associated signaling pathway." (PMID 31101684, 2019). "Moreover, the study carried out in glioma demonstrated that HSDL2 might regulate tumor progression through AKT-associated signaling pathway." (PMID 31101684, 2019). "A previous study showed that HSDL2 expression was upregulated in gliomas and was positively correlated with tumour grade." (PMID 35193614, 2022). "HSDL2 up-regulation has been observed in human glioma samples, and reported to have close relationship with tumor proliferation, cell cycle and apoptosis." (PMID 31101684, 2019). "The expression pattern of HSDL2 was positively correlated with aggressive progression of glioma." (PMID 31101684, 2019).
breast carcinoma (3 papers, 2021 to 2024). "The high expression of HSDL2 was presented in breast cancer tissues, related to high histological grades, late clinical stages and lower overall survival, even depletion of HSDL2 inhibited proliferation and induced cell cycle arrest in breast cancer." (PMID 35948893, 2022). "Additionally, Dong et al24 observed that HSDL2 was strongly positive staining in the breast cancer, and detected the correlation between highly expressed HSDL2 and LN metastasis, histological stage and worse prognosis." (PMID 33738911, 2021).
cervical cancer (3 papers, 2021 to 2023). A primary or metastatic malignant neoplasm involving the cervix. "This consequence substantially indicated the relevance between HSDL2 and the ability of migration and invasion of cervical cancer cells, and it was agreed again through the wound healing, migration and invasion assay." (PMID 33738911, 2021). "In this study, we found that the overexpression of HSDL2 was in relation with cervical cancer progression including lymph nodes metastasis and recurrence." (PMID 33738911, 2021). "The IHC assay was performed to investigate the expression of HSDL2 in 119 cervical cancer tissues, 29 CIN and 45 normal cervix tissues." (PMID 33738911, 2021). "To deeply investigate the function role of HSDL2 in cervical cancer cells, we constructed si‐HSDL2 using three different si‐RNAs and simultaneously overexpressed the HSDL2 in cervical cell lines (Hela, C33A and SiHa)." (PMID 33738911, 2021). "Most importantly, the new insights were given into the role of HSDL2 in the lipid metabolism of cervical cancer." (PMID 33738911, 2021). "Accordingly, we observed triglyceride and phospholipid were lessened in the HSDL2‐depleted cervical cancer cells, while the opposite result was shown in the HSDL2‐overexpressed cervical cancer cells." (PMID 33738911, 2021). "Oncomine database presented that the expression of HSDL2 was higher in cervical cancer and lower in non‐cancer tissues." (PMID 33738911, 2021). "HSDL2 also gave impetus to tumorigenesis by initiating and promoting proliferation, invasion and migration of cervical cancer cells (Hela, C33A and SiHa) through EMT." (PMID 33738911, 2021). "We first examined the strong staining in the species of cervical cancer through IHC, demonstrating that HSDL2 expression significantly correlated with the cervical cancer." (PMID 33738911, 2021). "More essentially, we provided evidence that HSDL2 exerts various effects on biological functions in cervical cancer cells and relates to patients' life span." (PMID 33738911, 2021). "Unfortunately, study on the mechanism of HSDL2 promoting cervical cancer through the lipid metabolism is limited till date." (PMID 33738911, 2021). "Meanwhile, our team also newly revealed that HSDL2 triggers the tumorigenesis through lipid metabolism in representative cervical cancer cell lines." (PMID 33738911, 2021). "Of note, HSDL2 overexpression was significantly related to poor prognosis of cervical cancer patients even including patients with early stage and without LN metastasis." (PMID 33738911, 2021). "The positive staining rates and strongly positive staining rates of HSDL2 in cervical cancer tissues are 87.39% (104/119) and 60.5% (72/119), respectively, much higher than in CIN (62.07%, 37.93%) and in normal tissues (26.67%, 2.22%) (P < .001)." (PMID 33738911, 2021). "In humans HSDL2 modulates cervical cancer cell proliferation and metastasis." (PMID 36845393, 2023). "To conclude, HSDL2 plays a fatal role in a variety of cervical cell functions, which indicated HSDL2 may become a novel target in biotherapy and prognosis of cervical cancer." (PMID 33738911, 2021). "But whether there is a correlation between HSDL2 and lipid metabolism in representative cervical cancer cell lines remains unclear." (PMID 33738911, 2021). "All these consequences significantly implied that HSDL2 is a novel but strong potential predictor as well as therapeutic target of cervical cancer, which could bring benefit to cervical cancer patients in the future." (PMID 33738911, 2021). "Subsequently, we detected from the wound healing assay that the wound closure area decreased as higher HSDL2 expression, consistent with it, migration and invasion assay exhibited that the cell migration and invasion abilities of cervical cancer cells obviously declined after HSDL2 knockdown." (PMID 33738911, 2021). "Next, we further investigated the prognostic value of HSDL2 expression in cervical cancer." (PMID 33738911, 2021).
cervical cancer (continued). "In addition, SREBP1 knockdown clearly repressed proliferation, migration and lipid metabolism by using siRNA in HSDL2‐overexpressing cells, implied that HSDL2 promoted progression of cervical cancer through lipid metabolism." (PMID 33738911, 2021). "Broadly speaking, we knew that HSDL2 regulates the proliferation, migration and invasion of cervical cancer cells and might be a new target of molecular therapy of metastatic cervical cancer." (PMID 33738911, 2021). "Human hydroxysteroid dehydrogenase‐like 2 (HSDL2) is a potent regulator in cancers and is also involved in lipid metabolism, but the role of HSDL2 in cervical cancer and whether it regulates the progress of cervical cancer through lipid metabolism remains unclear." (PMID 33738911, 2021). "However, the correlation between HSDL2 and cervical cancer remains elusive." (PMID 33738911, 2021). "Recently, Shang et al18, 19 observed that the long noncoding RNA LNMICC promotes lymph metastasis in the cervical cancer through reprogramming fatty acid metabolism, and several research studies suggested that HSDL2 might be a key factor of fatty acid regulatory in lipid metabolism." (PMID 33738911, 2021). "Besides, we found the overexpression of HSDL2 could be a determinant of cervical cancer development, such as clinical stage, LN metastasis and recurrence." (PMID 33738911, 2021). "Therefore, HSDL2 may involves in the initiation and development of cervical cancer, which could become a novel predictor of the cervical cancer." (PMID 33738911, 2021). "Hence, we speculated that HSDL2 may regulates development of cervical cancer either, and performed a series of assays to demonstrate the deduction." (PMID 33738911, 2021). "HSDL2 could serve as a novel marker of early diagnosis in cervical cancer." (PMID 33738911, 2021). "Compared to the control group, we found that epithelial marker E‐cadherin was up‐regulated in the si‐HSDL2 groups, while mesenchymal markers (Vimentin, Snail, Slug and MMP‐2) were considerably down‐regulated in all three cervical cancer cell lines." (PMID 33738911, 2021). "Hence, we wondered whether the failure of HSDL2 is lethal in the cervical cancer." (PMID 33738911, 2021). "However, there is no study on whether HSDL2 involves in the reprogramming of cervical cancer lipid metabolism." (PMID 33738911, 2021).
cholangiocarcinoma (3 papers, 2021 to 2023). A carcinoma that arises from the intrahepatic biliary tree (intrahepatic cholangiocarcinoma) or from the junction, or adjacent to the junction, of the right and left hepatic ducts (hilar cholangiocarcinoma). "However, the role of HSDL2 in cholangiocarcinoma (CCA) and the mechanism by which it regulates CCA progression by modulating ferroptosis are unclear." (PMID 37718459, 2023).
bladder cancer (2 papers, 2022 to 2025). "The expression of HSDL2 was upregulated in the human bladder cancer cell lines, and HSDL2 knockdown inhibited bladder cancer progression by reducing proliferation, promoting apoptosis in vitro or vivo." (PMID 35948893, 2022).
epilepsy (2 papers, 2023 to 2026). A brain disorder characterized by episodes of abnormally increased neuronal discharge resulting in transient episodes of sensory or motor neurological dysfunction, or psychic dysfunction. "The functions of Mvd, Lancl1, Aldh3b1 and Hsdl2 in epilepsy are still worthy to be explored in our future studies." (PMID 36894540, 2023).
lung adenocarcinoma (2 papers, 2020 to 2022). A carcinoma that arises from the lung and is characterized by the presence of malignant glandular epithelial cells. "The aims of the present study are to investigate the role of hydroxysteroid dehydrogenase-like 2 (HSDL2) in the progression of lung adenocarcinoma and illuminate the underlying molecular mechanisms." (PMID 32211805, 2020). "Shi’s researches suggested that HSDL2 was upregulated in the lung adenocarcinoma tissue and HSDL2 knockdown inhibited lung adenocarcinoma progression via downregulating AKT2 expression." (PMID 35948893, 2022). "We found that HSDL2 KD significantly suppressed the proliferation, cell cycle, clone formation, invasion and migration, and induced the apoptosis in lung adenocarcinoma cells in vitro." (PMID 32211805, 2020). "HSDL2 KD not only inhibited the proliferation, cell cycle, apoptosis, clone-formation, invasion and migration of lung adenocarcinoma cells in vitro (P<0.05), but also suppressed the growth and metastasis in vivo (P<0.05)." (PMID 32211805, 2020). "To further reveal the molecular mechanism of HSDL2 in the progression of lung adenocarcinoma, we looked for the downstream signaling pathways regulated by HSDL2 using gene chips (three replicate chips)." (PMID 32211805, 2020). "The mRNA expression level of HSDL2 in H1299 cell line was highest, so H1299 cell line was selected for subsequent experiments to verify the role of HSDL2 in the progression of lung adenocarcinoma using siHSDL2." (PMID 32211805, 2020). "HSDL2 functions as an oncogene to promote the growth and metastasis of lung adenocarcinoma via promoting the expression of AKT2." (PMID 32211805, 2020). "In the present study, results from IHC indicated that high HSDL2 expression is a poor prognosis factor in patients with lung adenocarcinoma." (PMID 32211805, 2020). "Results from in vitro experiments disclosed that HSDL2 KD inhibited the growth and metastasis of lung adenocarcinoma." (PMID 32211805, 2020). "In vitro and in vitro experiments showed that HSDL2 KD inhibited the growth and metastasis of lung adenocarcinoma." (PMID 32211805, 2020). "In the present study, we used short hairpin RNA (shRNA) technology to knockdown (KD) HSDL2 expression to investigate the role of HSDL2 in the progression of lung adenocarcinoma." (PMID 32211805, 2020). "Our data demonstrated that HSDL2 was up-regulated in lung adenocarcinoma tissue samples (P<0.001)." (PMID 32211805, 2020). "Our results showed that AKT2, BIRC3, and ERK are potential targets of HSDL2 in lung adenocarcinoma." (PMID 32211805, 2020). "In addition, we further detected the effects of HSDL2 KD on lung and liver metastasis of lung adenocarcinoma." (PMID 32211805, 2020). "HSDL2 is a novel potential target for molecular targeted therapy in lung adenocarcinoma." (PMID 32211805, 2020). "HSDL2 appears to be a novel potential target for molecular targeted therapy in lung adenocarcinoma." (PMID 32211805, 2020). "The present study is the first research investigating the role of HSDL2 in lung adenocarcinoma." (PMID 32211805, 2020). "Besides, HSDL2 KD could also suppress tumor growth and metastasis in lung adenocarcinoma mouse models." (PMID 32211805, 2020).
papillary thyroid cancer (2 papers, 2019 to 2020). "HSDL2 has promoting effects on tumor progression in papillary thyroid cancer, bladder cancer, ovarian cancer, and glioma, but has suppressing effects in cholangiocarcinoma." (PMID 32211805, 2020). "They conducted in vitro experiments to confirm that HSDL2 KD suppressed the proliferation and cycle, and promoted the apoptosis of papillary thyroid cancer cells." (PMID 32211805, 2020). "However, their bioinformatics analysis based on gene chips showed that AKT3, nuclear factor of activated T-cells, cytoplasmic 2 (NFATc2), and protein phosphatase 3 catalytic A (PPP3CA) were potential targets of HSDL2 in papillary thyroid cancer." (PMID 32211805, 2020).
Alzheimer disease (1 paper, 2023). A progressive, neurodegenerative disease characterized by loss of function and death of nerve cells in several areas of the brain leading to loss of cognitive function such as memory and language. "The critical roles of HSDL2 in the pathogenesis of various diseases, such as cancer, Alzheimer’s disease, and obesity, involve the modulation of signaling and metabolic pathways." (PMID 37718459, 2023).
bile duct cancer (1 paper, 2023).
diabetes mellitus (1 paper, 2024). A metabolic disorder characterized by abnormally high blood sugar levels due to diminished production of insulin or insulin resistance/desensitization. "Finally, we analyzed the relationships of the expression of the key genes (HSDL2, BCO2, CORIN, and SNORA80E) with that of transcription factors and regulatory genes in samples from patients with diabetes-associated heart failure." (PMID 38883603, 2024). "HSDL2, BCO2, CORIN, and SNORA80E may regulate cardiomyocyte cuproptosis in patients with diabetes mellitus-associated heart failure through effects on the immune system." (PMID 38883603, 2024).
endometriosis (1 paper, 2025). The growth of functional endometrial tissue in anatomic sites outside the uterine body. "Statistically significant differences were observed in the expression levels of six hub genes (ACSL4, CYP2C18, CYP2C9, HSD17B3, HSDL2, and PTGS2) between the Endometriosis and Control groups of the combined GEO datasets (p < 0.001)." (PMID 40313549, 2025).
hepatitis B virus infection (1 paper, 2023). A viral infection caused by the hepatitis B virus. "HSDL2 expression level was not significantly correlated with age, sex, histological grade, tumor location, lymphatic metastasis, distant metastasis, TNM stage, hepatitis B virus infection, tumor index, or liver function index in patients with CCA." (PMID 37718459, 2023).
lentivirus infection (1 paper, 2022). Virus diseases caused by the Lentivirus genus. "HSDL2 lentivirus infection elevated HSDL2 expression, while shRNA-HSDL2 infection inhibited HSDL2 expression." (PMID 35193614, 2022).
lung carcinoma (1 paper, 2020). "The results of RT-PCR using GAPDH as a reference gene indicated that the mRNA expression levels of HSDL2 in human lung cancer cell lines were significantly higher than that in human lung epithelial cell line." (PMID 32211805, 2020). "We compared the expression levels of HSDL2 in human lung cancer cell lines (H1975, A549, SK-MES-1, H1688, and H1299) and normal human lung epithelial cell line (BEAS-2B)." (PMID 32211805, 2020).
lymph node metastasis (1 paper, 2021). "Then, we detected the strongly positive staining of HSDL2 in both the samples of late stage and lymph node metastasis, the rates were respectively 61.2% (21/119) and 39.7% (57/119)." (PMID 33738911, 2021). "Especially, we detected the significant correlation between survival and HSDL2 expression in the patients with both early and late stage, lymph node metastasis and no metastasis." (PMID 33738911, 2021).